CD3D (CD3 delta subunit of T-cell receptor complex)
Diseases named in the same sentence as CD3D in open-access papers (continued):
Sharing a sentence is not in itself a finding about the gene and the disease.
Opportunistic infection (1 paper, 2019). An infection that is caused by a pathogen that would generally not be able to cause an infection in a host with a normal immune system. "Mutations in CD3δ (CD3D), CD3ε (CD3E), and CD3ζ (CD247) cause the T-B+NK+ SCID phenotype, resulting in profound lymphocyte impairment and increased susceptibility to opportunistic infections, in need of rescue by HSCT." (PMID 31921117, 2019).
Stroke (1 paper, 2022). Sudden impairment of blood flow to a part of the brain due to occlusion or rupture of an artery to the brain. "The upregulation of Cd3d, Cd3e, Cd3g, Blnk, Sdc1, and Jchain suggests that chronic inflammation persists in peri-infarct regions for at least 7 weeks after stroke." (PMID 34819339, 2022).
uveal melanoma (1 paper, 2022). A melanoma derived from melanocytes of the uveal tract. "CD3D upregulation has been associated with resistance to anti-tumor therapy in patients with uveal melanoma, which was attributed to tumor infiltration by increased numbers of immune-suppressive regulatory T-cells." (PMID 36291815, 2022).
tumor (134 papers, 2015 to 2026). "GSEA, categorizing genes into high- and low-expression groups based on CD3D levels, revealed significant enrichment of immune-related pathways associated with CD3D across all tumor types." (PMID 40702236, 2025). "To define tumor‐associated lymphocytes interacting with Carcinoma 3, we subclustered T lymphocytes based on the expression of CD3D and TRAC, yielding a total of 21,093 cells (nBCC = 6191, nSCCIS = 7981, and nSCC = 6921)." (PMID 40776410, 2025). "We analyzed the relationship between CD3D and currently known gene sets in the tumor microenvironment and verified the expression association between CD3D and CD8A in two other cohorts, GSE29721 and GSE121248." (PMID 34124275, 2021). "Noteworthy, FGL1 is positively associated with CD4+ T cell levels within the tumor, while it can also support the expression of CD3D and prevent that of FOXP3; hence, FGL1 may support T cell tumor infiltration and function in the cancer microenvironment." (PMID 36268014, 2022). "Expanding on this, CARs incorporating signaling domains from CD3δ or CD3γ in the context of the 41BB co-stimulatory domain show enhanced anti-tumor efficacy, reduced tonic signaling, and lower cytokine secretion compared to BBζ CARs." (PMID 41601693, 2026). "After proteins of interest were identified, we switched to the detailed line chart views to measure SOX10 (a tumor marker) and CD3D (immune marker), HLAA (marking cell membrane), along with inhibitory pathway PDL1-PD1." (PMID 39255170, 2025). "Consistent with the IHC data, patients with higher tumor expression of CD3D/E/G genes at progression showed significantly longer survival; median OS was 42 months for above-median vs. 11 months in the below-median group." (PMID 40239619, 2025). "Consistent with this, spatial transcriptomic analysis using Xenium showed differential localization of T cells (Cd3d, Cd3e, Cd3g, Cd8a, Cd8b1, and Cd4) within tumor sections of RPR2 and CRPR2 mice." (PMID 41353272, 2025). "In the example of melanoma, high SOX10 levels co-staining with DNA identify tumor cells, whereas CD3D forming a circle around a cell indicates the boundaries of a cell with the potential for tumor-cell killing." (PMID 39255170, 2025). "Canonical markers were used to annotate different cell types: malignant cells (COL1A1, IBSP), myeloid cells (CD74, CD14), osteoclasts (CTSK, MMP9), pericytes (RGS5, ACTA2), endothelial cells (PECAM1, VWF), and tumor-infiltrating lymphocytes (CD3D, NKG7)." (PMID 40730548, 2025). "Our observations revealed CD3D+ T cells accumulating in clusters within the tumor area and tumor boundary, with IGHG1+ plasma cells and CCL19+ fibroblasts scattered within these T cell clusters." (PMID 39505867, 2024). "Specifically, apart from CD3D, all identified signature genes exhibited significant upregulation in tumor cells." (PMID 38918587, 2024). "Multiple immune-associated genes such as CD79A, CD3E, CD3D, ZAP70, CXCR6, and GZMA were upregulated in hot tumor regions." (PMID 38803565, 2024). "We annotated these clusters with canonical cell-type markers and identified tumor cells expressing Epcam and Nkx2-1, B cells expressing Cd19, T cells expressing Cd3d, and NK cells expressing Ncr1." (PMID 39718828, 2024). "Then we used Loupe Browser 7.0 to group spots with gene characteristics (log2 count > 0) of CD68 or CD4 with CTLA4 as THC, and spots with gene characteristics of CD3D or CD3E or CD3G as tumor immune cells." (PMID 39499374, 2024). "The results revealed that CD3D expression was higher in tumor cases than in normal ones across most types of cancer, suggesting its potential as a therapeutic target." (PMID 39247606, 2024). "CD3D has been closely related to tumor prognosis, immune microenvironment and immunotherapy responsiveness." (PMID 37349706, 2023).
tumor (continued). "When overlaying gene expression of CXCL9, CD3D (t cells) and CD68 (macrophages), we see moderate spatial correlation with CXCL9 and CD3D (r = 0.4, p = 3E-29) along the tumor-stromal interface, and weaker correlation with CD68 (r = 0.17, p = 1E-10)." (PMID 36906603, 2023). "We found that TMEM41A overexpression was correlated with EC stromal, immune, and estimate scores and was linked with tumor purity, immune cells (such as the macrophages, CD8 T cells, and TFH), and immune cell markers (such as the CD8A, CD3D, and CD3E)." (PMID 37478120, 2023). "To better understand the transcriptional heterogeneity in tumor-infiltrating T lymphocytes (TILs), we identified T- cell clusters that expressed known T- cell markers (CD3D and CD3E)." (PMID 36569924, 2022). "The average number of CD3D-positive cells in the tumor tissues was 195.45 ± 10.96, while that in the paracancerous tissues was 107.23 ± 6.05, indicating a significant difference (P<0.000)." (PMID 35719985, 2022). "Kaplan–Meier survival analysis indicated that the 5-year overall survival rate of patients with high CD3D expression in tumor tissues was 57.4%, while that of patients with low CD3D expression was 46.1%, showing a significant difference (P=0.006)." (PMID 35719985, 2022). "To better under the transcriptional heterogeneity within tumor-infiltrating T lymphocytes (TILs), we identified T cell clusters expressing the known T-cell marker (CD3D)." (PMID 35515000, 2022). "The enrichment of T-cells and fibroblasts/endothelial cells in tumor tissues was verified through immunofluorescent staining of CD3D and SPARC, respectively." (PMID 35974387, 2022). "Using immunohistochemistry and single-cell sequencing analysis, we found that CD3D antibody staining was weaker in tumor tissues than normal tissues and was related to CD8+ T cells." (PMID 34124275, 2021). "Analysis of the GEPIA also indicated that CD3D expression levels were higher in tumor tissues than in normal tissues." (PMID 33350431, 2021). "By mining TCGA gene expression data, the mRNA expression of CD3D in tumor samples was significantly higher than that in normal samples." (PMID 33350431, 2021). "Genes such as CD3D and CD3G encode T cell surface glycoproteins and are well-known players in anti-tumor immunity." (PMID 32605588, 2020). "The expression of CD3D, CD3G, CXCL9, and IRF1 were significantly associated with tumor stage and distant metastasis." (PMID 32925784, 2020). "Further, to examine human IP-10 levels related to T cell infiltration within patient tumors, expression data for IP-10 and CD3D in clinical tumor specimens were examined from multiple published datasets." (PMID 31393905, 2019). "The cell populations inferred from this analysis were readily matched to the tumor cells and infiltrating lymphocytes, including macrophages and T cell classes, based on the specific expression of known markers such as CD3D and CD68." (PMID 29079795, 2017). "Incorporating the cytoplasmic tails of CD3ε, CD3γ, and CD3δ into CAR constructs has been shown to improve anti-tumor responses, while lowering cytokine secretion and early exhaustion compared to second-generation ζCARs, challenging the current gold-standard of ζ-based CAR T-cell therapy." (PMID 41601693, 2026). "These ROIs were selected based on the presence of PanCK+ tumor regions directly adjacent to dense CD3D+ and CD68+ immune infiltrates, identified through both H&E and multiplex immunofluorescence staining, to capture tumor margins involved in immune interaction." (PMID 40776410, 2025).
tumor (continued). "Tumours with a low MITF expression showed an increase in the numbers of CD3D (p = 0.048), CD8A (probe 3: p = 0.01), and CD68 (two probes, p = 0.001 and p = 0.004) cells, as well as a higher expression of HLA-A (three probes: p = 0.003, p < 0.001, and p = 0.002) and HLA-B (p = 0.004)." (PMID 37240204, 2023). "And as tumor Grade advanced, CD3D expression levels were increasingly up-regulated." (PMID 37386390, 2023). "CD3E and CD3D play important roles in the positive regulation of T-cell activation and leukocyte cell–cell adhesion and are considered to be the main determinants of tumor immunotherapy efficacy." (PMID 37509334, 2023). "In addition, CD3D was negatively correlated with the tumor location, Borrmann type and distant metastasis (P=0.012 for tumor location; P=0.007 for Borrmann type; P=0.027 for distant metastasis)." (PMID 35719985, 2022). "Moreover, FGL1 was positively associated with the CD3D expression and negatively associated with FOXP3, S100A9, and TPSB2 within the tumor site." (PMID 36268014, 2022). "In conclusion, CD3D may play an important regulatory role in the tumor immune microenvironment by regulating tumor infiltrating lymphocytes (TILs) and immune checkpoints and may be a potential immunotherapy target." (PMID 35719985, 2022). "The differential expression of CD3D in tumor tissues and paracancerous tissues." (PMID 35719985, 2022). "However, anti-PD-L1 treatment resulted in upregulation or downregulation of numerous genes in CD45+ tumor-infiltrating immune cells in TCh3 tumors, including Cd3d, Cd3e, Cd3g, Cd8a, Cd8b1, Nkg7, Ccl5, Ets1, Icos, Cxcr6, Pdcd1, Lag3, Prf1, and Gzmb (right)." (PMID 35366939, 2022). "Our data demonstrated that GPX8 was correlated with mRNA expression of immune markers of CD8+ T cells (CD8B), CD4+ T cells (CD4), T cells (CD3D), macrophages (CD68 and ARG1), neutrophils (ITGAM and CCR7), dendritic cells (NRP1), NK cells (B3GAT1), and tumor-associated fibroblasts (FAP)." (PMID 36061208, 2022). "Since CD2, CD3D, CD3E, and CXCR6 predict very favorable prognosis in CSCC, we evaluated the association of this new signature at transcriptomic level with the presence of tumor-infiltrating immune cell populations in CSCC." (PMID 34692491, 2021). "Based on the known annotation of marker genes from the literature, we grouped cells of nine clusters into four cell types: GNP-like tumor cells (expressing Math1 and Grin2b), microglia (expressing Aif1 and Cd68), T cells (expressing Cd3d and Cd3e), and endothelial cells (expressing Cldn5 and Cdh5)." (PMID 34210306, 2021). "The expression levels of CD8A (encoding CD8, marker of CD8+ T cells), CD4 (encoding CD4, marker of CD4+ T cells), and CD3D (encoding CD3, marker of T cells) were also significantly high in the low-risk groups, indicating higher abundance of the tumor suppressor T-cell subpopulation." (PMID 34641822, 2021). "In addition, the expression of MHC class II molecules, such as HLA-DR, in tumor tissue has been linked to the presence of tumor-infiltrating lymphocytes (TILs) and high expression of CD4, CD3D, and CD8A." (PMID 34439290, 2021). "The studies reveal that tumor samples expressed higher levels of CD3D." (PMID 33350431, 2021). "In addition, we also found that the CD3D, CD3E and LCK expression was significantly negatively related to tumor purity while positively associated with the infiltrating levels of immune cells, such as B cell, CD8 + T cell, and CD4 + T cell." (PMID 33748188, 2021). "The 8 SNPs (CD3EAP rs967591, TNFRSF10B rs1047266, AKT1 rs3803300, C3 rs2287845, HOMER2 rs1256428, GNB2L1 rs3756585, ADAMTSL3 rs11259927, and CD3D rs3181259) were found to be significantly associated with OS and/or DFS when adjusted for age, gender, smoking status, tumor histology, pathologic stage." (PMID 26462029, 2015).
tumor (continued). "Moreover, the dual targeting CD19/CD3ε + TAG‐72/CD3δ or CD19/CD3ε + TAG‐72/CD3γ FP T cells killed TAG‐72hi CD19lo tumor cells, while the CD19/CD3ε single targeting FP T cells could not eradicate CD19lo cells." (PMID 38023726, 2023). "However, in contrast with a previous publication, we did not observe a difference between tumor types in regard to the expression of genes associated with tumor-infiltrating lymphocytes, such as CD3D." (PMID 28049147, 2017). "ITGA5+ PanCK+ tumor cells, corresponding to the Carcinoma 3 cluster, were localized at the tumor–stroma boundary, and CXCR6+ FOXP3+ CD3D+ regulatory T cells were observed in close proximity within the adjacent stroma." (PMID 40776410, 2025). "Conversely, SURF4 overexpression in T cells significantly reduced the expression of activation markers (CD3D, CD69) and anti-tumor proteins (GZMB), while simultaneously suppressing the p-STING/p-IRF3 axis." (PMID 40846839, 2025). "BayeSpace‐enhanced spatial data revealed the abundant infiltration of T cells (CD3D, IL7R), B cells (MS4A1, MZB1), and cytotoxicity markers (GZMK) throughout tumor sections of HT samples, presenting an “immune‐activation” TME after HAIC therapy." (PMID 39686623, 2025). "Based on histological features and immunostaining for SYTO13, PanCK, CD3D, and CD68, we selected eight regions of interest (ROIs) and defined segments representing tumor cells (SCC_Tumor, PanCK+, n = 8) and the surrounding TME (SCC_TME, PanCK‐, n = 8)." (PMID 40776410, 2025). "The canonical markers EPCAM and KRT19 identified tumor cells, while CD3D, CD2, PTPRC, CD14, AIF1, CD79A, and COL1A2 validated non-tumor cells." (PMID 39955556, 2025). "Tumor cells were identified using EPCAM, KRT18, and AFP as markers, while T/NK cells were identified by using the markers CD3D, CD3E, and GZMA." (PMID 40740783, 2025). "Research indicates that SELENOP+ Mac can promote anti-tumor immunity by highly expressing FOLR2, IL32, CD3D, and LTC4S and are therefore considered to have anti-tumor effects." (PMID 38755647, 2024). "This single cell transcriptomic analysis allowed us to identify the presence of macrophages (CD163), T cells (CD3D), and pericytes (PDGFRB), as well as endothelial (VWF) and folliculostellate (SOX2) cells, within the tumor microenvironment." (PMID 39217365, 2024). "Firstly, it exerts an anti-tumor effect by activating the JAK2-STAT3 pathway, which upregulates CD3D and then promotes T-cell activation." (PMID 39247606, 2024). "IHC staining showed stronger expression of CD3D, CD3E, CXCR3 and IL2RG in tumor tissue compared to normal tissue." (PMID 37509334, 2023). "We propose that CARs containing the CD3δ ICD transmit self-restrained signals that favor self-renewing properties while preventing dysfunction, thus explaining their superior anti-tumor efficacy in vivo." (PMID 37932456, 2023). "Other cell type‐specific markers were similarly detected in the primary tumours (CDH2, CD3D and CD79A), including a notably low detection of CD19 in B cell populations." (PMID 37691350, 2023). "Our data indicated that the “cold” tumor types like MB and EPN also contained the major classical immune cells, such as T cells (PTPRC, CD3D), B cells (CD79A, IGHG1, MZB1), and NK cells (KLRB1)." (PMID 38094301, 2023). "The main cell clusters included T cells (CD3E and CD3D), B cells (CD19), natural killer cells (NCAM1, FCGR3A and KLRD1), myeloid cells (CD86 and CD163) and tumor cells (EPCAM, KRT8 and KRT18)." (PMID 36497182, 2022). "Some well-known marker genes were used to identify cell types, such as EPCAM and KRT19 for tumor cell, COL1A1 and ACTA2 for CAF, CD3D and CD3E for T cell, and CD68 and CD14 for macrophage." (PMID 36499343, 2022). "Unexpectedly, the C8 population of cancer cells expressed T-cell markers (CD3D, CD3E, CD7), which is recognized as a dual identity of T cells and tumor cells involved in the role of the TME." (PMID 36451812, 2022).